HGF (hepatocyte growth factor)
Diseases named in the same sentence as HGF in open-access papers (continued):
Sharing a sentence is not in itself a finding about the gene and the disease.
endometriosis (continued). "The epithelium of the endometriosis lesion expresses high levels of IGF-1R and c-MET, the receptor for IGF1/2 and HGF, respectively." (PMID 35740424, 2022). "The levels of MCP-1, HGF, and IGF-1 in serum and PF in women with endometriosis were significantly higher than the controls (P < 0.05–P < 0.001)." (PMID 34930225, 2021). "PF macrophages are regulated by ovarian steroids with respect to HGF and vascular endothelial growth factor (VEGF) secretion in women with endometriosis." (PMID 33980258, 2021). "Previous studies have found a higher level of IGF and HGF in the peritoneal fluid from endometriosis patients than in those without endometriosis, and the level of HGF correlated positively with the revised American Society of Reproductive Medicine score." (PMID 35740424, 2022). "The gene expression of HGF in PBMCs of patients with and without endometriosis after 1,25(OH)2D3 treatment compared with untreated controls showed a significant reduction after 24 h (p < 0.01 and <0.05, respectively)." (PMID 36259314, 2022). "Furthermore, we evaluated the expression of MCP-1, HGF, and IGF-1 by peritoneal fluid mononuclear cells (PFMCs), peripheral blood mononuclear cells (PBMCs), and ESCs in women with endometriosis compared to controls." (PMID 34930225, 2021). "In this case, resveratrol biological effect in terms of decrease in IGF-1 and HGF protein production was reported for both eutopic and ectopic endometrial stromal cells from women with endometriosis but not for cells from controls." (PMID 34444692, 2021). "Apart from VEGF-A, hepatocyte growth factor (HGF), as a pleiotropic cytokine, has angiogenic, mitogenic, and motogenic activities all of these may be involved in the pathogenesis of endometriosis." (PMID 31906916, 2020). "Increased HGF expression has been shown in ectopic compared to eutopic endometrial tissue in patient with endometriosis or non-endometriotic patients." (PMID 31906916, 2020). "Similarly, in the peritoneal fluid of women with endometriosis, levels of CXCL1, CXCL2, CCL2, MCP-3, and HGF were found to be significantly elevated compared to those in control individuals." (PMID 31636643, 2019). "Hepatocyte growth factor (HGF) was suggested to be elevated in women with endometriosis, although this was not confirmed in an additional study." (PMID 26240814, 2015). "Other proangiogenic factors, namely, IL-8, hepatocyte growth factor (HGF), erythropoietin, angiogenin, macrophage migration inhibitory factor, neutrophil-activating factor, and TNF-α, are all found at increased concentrations in the peritoneal fluid of patients with endometriosis." (PMID 23766765, 2013). "However, except for a report showing an increase in c-Met (RTK) and HGF (ligand) in endometriosis, there has been little evidence that RTK are overexpressed or activated in this disease." (PMID 19055724, 2008). "There is no doubt that endometriosis patients show elevated levels of expression and release of a range of proinflammatory cytokines and growth factors, including IL-1, IL-6, IL-8, epidermal growth factor and hepatocyte growth factor, in their ectopic and eutopic endometrium and peritoneal fluid." (PMID 36359004, 2022). "In this study, we compared the concentrations of MCP-1, HGF, and IGF-1 in serum and PF of patients with and without endometriosis." (PMID 34930225, 2021). "These unclear data on MCP-1, HGF, and IGF-1 expression, hinder the understanding of the physiologic role of signaling in women with endometriosis, and no comprehensive study has examined all of the involved cells in endometriosis concurrently." (PMID 34930225, 2021). "According to our knowledge, this study is the first study to investigate the effect of 1,25(OH)2D3, the active form of vitamin D, treatment on MCP‐1, HGF, and IGF‐1 gene and protein expression in PBMCs, PFMCs, and ESCs of patients with and without endometriosis." (PMID 36259314, 2022).
endometriosis (continued). "Recently, significantly higher concentrations of SCGF-β, IL-8, HGF, and MCP-1 have been reported, as well as lower levels of anti-inflammatory cytokine IL-13 in endometriosis patients such as those found in women without endometriosis." (PMID 32063886, 2019).
renal fibrosis (33 papers, 2009 to 2025). A final common manifestation of a wide variety of chronic kidney diseases characterized by glomerulosclerosis and tubulointerstitial fibrosis. "The results demonstrate that elevated urinary excretions of the markers of tubular injury (RBP-4, GST-π) and renal fibrosis (Col1, Col4), as well as HGF, an antifibrotic regulator, are associated with the albuminuric pattern of CKD in subjects with T2D." (PMID 36836700, 2023). "In the UUO mice model, exogenous HGF restored the expression of Adamts5 and ameliorated renal fibrosis induced by Men1 deficiency." (PMID 35968938, 2022). "Strikingly, exogenous HGF administration significantly ameliorated the Men1 deficiency‐induced degree of kidney injury and the severity of renal fibrosis in the mice that underwent UUO compared with that in the vehicle group, as determined by H&E, IHC and Western blot analysis." (PMID 35968938, 2022). "These factors along with HGF have been shown to exert antifibrotic effects involved in the attenuation of myocardial, pulmonary, hepatic, and renal fibrosis." (PMID 38185658, 2024). "The exacerbated unilateral ureteral obstruction (UUO) models in the Men1f/f and Men1∆/∆ mice were used to assess the pharmacological effects of rh‐HGF on renal fibrosis." (PMID 35968938, 2022). "Intriguingly, HGF seems to suppress chronic renal failure, and administration of HGF improves renal fibrosis." (PMID 35806457, 2022). "The previous studies have reported that HGF plays a vital role in the mesenchymal‐to‐epithelial transition and the progression of renal fibrosis." (PMID 35968938, 2022). "Altogether, these results further support the renoprotective roles of the MEN1 gene in the pathogenesis of kidney fibrosis and demonstrate that pharmacological intervention with rh‐HGF significantly ameliorated Men1 deletion‐exacerbated renal fibrosis." (PMID 35968938, 2022). "Under the action of heme oxygenase-1 (HO-1), bone morphogenetic protein-7 (BMP-7), and hepatocyte growth factor (HGF), renal fibrosis can be blocked or even reversed." (PMID 31781634, 2019). "To date, several factors, such as hepatocyte growth factor and Klotho, have been reported to have a therapeutic potential for renal fibrosis by reducing fibrogenic cytokine production as well as fibronectin and type I collagen deposition." (PMID 28585867, 2017). "AAV vectors serotype 9, designed for expression of hepatocyte growth factor (HGF), which is an anti-fibrotic cytokine, showed remarkable attenuation of tubulointerstitial fibrosis in a mouse model of renal fibrosis." (PMID 30410705, 2017). "HGF has long been recognized as an important factor in kidney regeneration and attenuation of renal fibrosis in several different animal models." (PMID 28191776, 2017). "Because of its inhibitory effect on fibrosis, HGF protein delivery or HGF gene therapy approaches improved renal fibrosis and renal dysfunction." (PMID 26670567, 2015). "Meanwhile, some other mediators are found to exert marked anti-fibrotic effects in the pathogenesis of renal fibrosis, such as HGF (hepatocyte growth factor), EPO (erythropoietin) and BMP-7 (bone morphogenetic protein-7)." (PMID 24844766, 2014). "HGF has also been reported to inhibit renal inflammation, proinflammatory chemokine expression and renal fibrosis in an UUO model." (PMID 20412564, 2010). "We further attempted to evaluate the pharmacological effects of rh‐HGF on renal fibrosis in vivo." (PMID 35968938, 2022). "Next, we investigated whether the HGF/Met pathway is involved in renal fibrosis in DN patients using immunofluorescence staining with a phosphorylation-specific cMet antibody (Ab) to determine the levels of active cMet." (PMID 30143691, 2018). "Additionally, PGD2 binding the DP receptor inhibits TGF-β-induced collagen secretion and, in hepatic and renal fibrosis, HGF administration significantly reduced the deposition of extracellular matrix." (PMID 29348826, 2017).
renal fibrosis (continued). "Previously, we found that AM could significantly inhibit the renal fibrosis by up-regulating hepatocyte growth factor (HGF) and down-regulating transforming growth factor-β1 (TGF-β1)." (PMID 24942185, 2014). "Of note, hepatocyte growth factor (HGF) is a potent antifibrotic cytokine that has been reported to have an antifibrotic function in various pathological conditions, such as pulmonary, liver and renal fibrosis." (PMID 24840640, 2014). "HGF inhibition exacerbates renal fibrosis, whereas HGF supplementation reverses progression." (PMID 22460762, 2012). "Abnormal activation of several cell growth factors such as transforming growth factor beta (TGF-β), connective tissue growth factor (CTGF), angiotensin II (Ang II), hepatocyte growth factor (HGF), and their receptors are the mediators of renal fibrosis." (PMID 39308629, 2024). "Patients with T2D have elevated urinary excretion of markers of tubular injury (RBP-4, GST-π), renal fibrosis (Col1, Col4), and antifibrotic growth factors (BMP-7, HGF)." (PMID 36836700, 2023). "CGA regulates the expression of HGF and protects from renal fibrosis, but the process of CGA regulation of HGF needs to be further studied to obtain accurate results." (PMID 35845802, 2022). "Strikingly, exogenous rh‐HGF reduced ECM accumulation and blocked renal fibrosis in the obstructed kidneys of the Men1Δ/Δ mice after UUO." (PMID 35968938, 2022). "Studies have also indicated that the actions of fibrotic factors and cytokines, such as TGF-β1, HGF, CTGF, α-SMA, and MCP-1, play significant roles in the progression of renal fibrosis in early DN." (PMID 27725943, 2016). "Fibrosis reduction: MSCs decrease the levels of profibrotic factors such as IL-6, IL-1β, TNF-α, TGF-β, α-SMA, collagen I, and collagen IV while increasing the levels of antifibrotic factors such as FGFs, HGF, and VEGF, all of which inhibits EMT and reduces renal fibrosis." (PMID 40093796, 2025). "TGF-β1 has been deemed to serve as the predominant mediator of the pathology of renal fibrosis, whereas interferon-γ (IFN-γ), hepatocyte growth factor (HGF) and bone morphogenetic protein 7 (BMP-7) inhibit the production of matrix components primarily by counteracting TGF-β1 action." (PMID 34356613, 2021). "HGF is primarily produced in nonepithelial cells, such as fibroblasts and pericytes, and is able to block myofibroblast activation and therefore renal fibrosis." (PMID 28191776, 2017). "HGF might inhibit TGF-β1 expression and prevent the progression of renal fibrosis in various animal models." (PMID 27725943, 2016). "Additionally, the roles of profibrogenic factors and interstitial cytokines, including TGF-β1, HGF, CTGF, α-SMA, and MCP-1, during the progression of renal fibrosis were assessed in early DN." (PMID 27725943, 2016). "Vitamin D inhibits renal fibrosis through multiple mechanisms, including direct interaction with Smad3 to block TGF-β–Smad signal transduction, and by independently stimulating the expression of hepatocyte growth factor (HGF) in the liver, which prevents renal myofibroblast generation." (PMID 40305356, 2025). "We demonstrated that WJ-MSCs can restore the disturbed balance of HGF/TGF-β1 during fibrogenesis via induction of native and foreign HGF synthesis in host renal TECs at the initial stage of ischemic AKI, as a result of which tubular EMT delay and rescue of renal fibrosis occur." (PMID 23734757, 2013). "Similar to their effect on renal fibrosis, irbesartan, but not losartan, treatment significantly reduced fibrosis in the heart, whereas the reduction of fibrosis in the heart by irbesartan was also attenuated by treatment with GW9662, a PPARγ antagonist, or anti‐HGF neutralizing antibody." (PMID 23608606, 2013).
bladder cancer (31 papers, 2002 to 2025). "To gain a further understanding surrounding the mechanisms of hepatocyte growth factor (HGF)-induced migration, we designed a loss-of-function screen to identify phosphatases that alter migration in the bladder cancer cell line NBT-II cells." (PMID 38102334, 2023). "In this study, we evaluated the therapeutic effect for bladder cancer cells by the inhibition of HGF activation through overexpression of HAIs." (PMID 40299447, 2025). "In bladder cancer, for instance, CAFs significantly contribute to disease progression by releasing factors such as the Hepatocyte Growth Factor (HGF) and VEGF, which aid in tumor development and spread." (PMID 38249783, 2024). "In bladder cancer, the major source of increased serum HGF levels is likely the tumor itself; several studies have demonstrated the involvement of the HGF/MET pathway in the development of aggressive tumors." (PMID 34997350, 2022). "The effect of some of the currently used factors, such as the Wnt/β-catenin and MAPK modulators, noggin, and hepatocyte growth factor, remains to be established in bladder cancer." (PMID 35565191, 2022). "A recent study found that abnormal HGF/c-Met upregulation and activation are often observed in bladder cancer." (PMID 32863765, 2020). "HGF and soluble Met levels are highly expressed in the serum of bladder cancer patients, positively correlating with disease progression." (PMID 31554791, 2019). "However, the mechanisms underlying HGF/c-MET-mediated invasion in bladder cancer remains unknown." (PMID 31554791, 2019). "Cabozantinib has been reported to inhibit MMP-1 expression by blocking the HGF-MET signaling pathway in bladder cancer cells." (PMID 31781483, 2019). "Here, the authors show that HGF induces EMT and invasion by stabilising TGFβ receptor through inhibition of the SMURF2 ligase, and the combined blockade of MAPK and TGFβ pathways suppresses HGF-mediated bladder cancer progression." (PMID 31554791, 2019). "Taken together, these results suggest that HGF induces an early TβR expression signature required for EMT in bladder cancer." (PMID 31554791, 2019). "In this regard, several reports have indicated that HGF/c-Met pathway activation correlates with bladder cancer progression." (PMID 26474384, 2015). "The HGF/Met pathway was characterized in several UC-derived cell lines to better define its prevalence and functionality in bladder cancer." (PMID 25534569, 2014). "It has also been reported that patients with urinary bladder cancer have elevated levels of HGF in urine and bladder cancer tissue." (PMID 18549507, 2008). "This suggested that ligand-dependent activation of MET was critical in bladder cancer, and the inhibition of HGF activation by HAI-1 might have the potential to regulate the progression of cancer." (PMID 40299447, 2025). "However, the interaction between FGFR and HGF-MET signaling in bladder cancer progression remains largely unexplored." (PMID 41315241, 2025). "Furthermore, stratification of bladder cancer patients into two groups based on the HGF expression determined that patients with high HGF expression had significantly reduced overall survival." (PMID 31554791, 2019). "Conversely, HGF was able to rescue FGFR3 inhibition in bladder cancer cells." (PMID 27655711, 2016). "Moreover, HGF was reported to override the motility-inhibitory effect of KAI1/CD82 in YTS1 bladder cancer cells and Du145 cells." (PMID 23251627, 2012). "An early report claimed that human β-cells were able to replicate efficiently (69% of BrdU/insulin double-positive cells) when exposed to a specific matrix (matrix produced by the rat bladder carcinoma cell line 804G) in the presence of hepatocyte growth factor/scatter factor (HGF/SF)." (PMID 22007286, 2011). "Therefore, we hypothesize that HAI-2 may also inhibit the growth of bladder cancer by the inhibition of pro-HGF activation." (PMID 40299447, 2025).
bladder cancer (continued). "Tumor-infiltrating neutrophils secrete HGF, which activates MET signaling in bladder cancer cells, promoting proliferation, invasion, and EMT." (PMID 41315241, 2025). "Bladder cancer cells dispatch exosomes containing LINC00665 to CAFs, stimulating their activation and secretion of hepatocyte growth factor (HGF), which promotes lymphangiogenesis and lymph node metastasis." (PMID 39717771, 2024). "One report on bladder cancer cell lines (5637, T24, J82, HT1376, and MGHU-1 cells) demonstrated that CM from FB increased the invasion capacity and identified secreted HGF as one mediating soluble factor." (PMID 37781195, 2023). "In bladder cancer, however, few studies have investigated the impact of circulating HGF, and due to limitations of their sample size and study design, the significance and clinical utility of blood levels of HGF for the prediction of worse pathologic or poor survival outcomes remains unclear." (PMID 34997350, 2022). "Patients with bladder cancer present urothelial cell cycle dysregulation including aberrant activity of CDK4, while overexpression of HGF is known to be involved in early stages of carcinogenesis." (PMID 34232958, 2021). "Our results demonstrate that the HGF/MET-Pyk2 signaling axis confers resistance to the novel FGFR inhibitor, and this mechanism is common for lung, gastric, and bladder cancer cells." (PMID 33898310, 2021). "Collectively, these observations indicate that HGF/MET signaling triggers a Pyk2-mediated mechanism of resistance to FGFR inhibitor that appears to be common in lung, gastric, and bladder cancer cells." (PMID 33898310, 2021). "In this review, we summarized the significance of pericellular pro-HGF activation in PC, RCC, and bladder cancer." (PMID 32290402, 2020). "To identify the mechanisms through which HGF and its cognate receptor, c-MET, induces EMT in bladder cancer we treated the rat bladder carcinoma cell line NBT-II, with either HGF or EGF and analysed changes in cellular morphology with EMT marker expression." (PMID 31554791, 2019). "Aberrant HGF/c-MET upregulation and activation is frequently observed in bladder cancer correlating with cancer progression and invasion." (PMID 31554791, 2019). "Taken together, these results suggest that TGFβ signalling is required for HGF-mediated EMT induction, and invasion in bladder cancer cell lines." (PMID 31554791, 2019). "As HGF leads to TGFβ-mediated EMT in NBT-II cells, we explored if the TGFβ pathway was essential for tumourigenesis, EMT and invasion in bladder cancer." (PMID 31554791, 2019). "The elevated levels of HGF in patients with MIBC compared with patients with superficial bladder cancer suggests that HGF has a role in inducing EMT and invasion in bladder cancer progression." (PMID 31554791, 2019). "First, SMURF2 inhibition by c-SRC upregulates the TβR pathway by stabilising TGFβR complex a function we define to be critical for HGF-induced EMT and invasion in vitro and tumour progression in vivo in bladder cancer." (PMID 31554791, 2019). "The function of miRNAs-HGF/c-MET axis in several human cancers has also been explored, including NSCLC, renal cancer, breast cancer, bladder cancer, and other cancers." (PMID 30360560, 2018). "Over 20 years ago, our laboratory identified the combination of hepatocyte growth factor/scatter factor (HGF/SF) and the HTB-9 extracelluar matrix from human bladder carcinoma cells, as potent stimuli for β cell replication." (PMID 28702240, 2016). "Notably, bladder cancer tissues, particularly MIBC, exhibit high levels of infiltrated neutrophils, which are known to secrete HGF." (PMID 41315241, 2025). "In addition, no apparent statistical correlation was also observed between the expression of HGF, MET, ST14, HPN, and HGFAC and the prognosis of patients with bladder cancer by GEPIA." (PMID 40299447, 2025).